IL25 (interleukin 25)
Diseases named in the same sentence as IL25 in open-access papers (continued):
Sharing a sentence is not in itself a finding about the gene and the disease.
lung carcinoma (7 papers, 2016 to 2023). "Since MVP causes chemoresistance in lung cancer, an increase in IL-25 and MVP would greatly aggravate chemotherapy resistance in lung cancer patients." (PMID 37005677, 2023). "In mice bearing heterotopic lung cancer, adoptive transfer of IL-25-activated ILC2s led to increased tumor growth, increased metastasis and reduced survival." (PMID 37781372, 2023). "To date, the role of IL-25-activated ILC2 cells in a murine model of lung cancer remains unexplored." (PMID 37781372, 2023). "This is the first time that IL25-activated ILC2 cells’ role in lung cancer has been studied and our results indicate that such cells bear tumor-promoting functions, in contrast to IL-33-activated ILC2 cells." (PMID 37781372, 2023). "Adoptive transfer of IL-25-activated ILC2 cells in lung cancer-bearing mice led to increased tumor burden, increased metastasis, and reduced survival." (PMID 37781372, 2023). "Together, these findings suggest, in addition to inducting anti‐apoptosis, IL‐25 promotes cisplatin resistance of lung cancer cells partly by activating NF‐κB signaling pathway to increase the expression of MVP." (PMID 31044552, 2019). "Together, these data suggested that extracellular secreted IL‐25 promotes the formation of cisplatin resistance in lung cancer cells." (PMID 31044552, 2019). "The role of IL‐25 in cisplatin tolerance of lung cancer cells was also investigated in animal model." (PMID 31044552, 2019). "To further illustrate how IL‐25 regulates cisplatin resistance of lung cancer cells, we examined the expression of MVP, which is a well‐known multidrug‐resistant protein, in cisplatin‐resistant A549/CDDP cells." (PMID 31044552, 2019). "Further study revealed that IL‐25 regulates cisplatin resistance of lung cancer cells by mediating the expression of MVP." (PMID 31044552, 2019). "Taken together, we believe that the up‐regulation of IL‐25 induces MVP expression contributing to chemotherapy resistances of lung cancer cells." (PMID 31044552, 2019). "The role of IL-25-activated ILC2 cells in lung cancer remains to be addressed." (PMID 37781372, 2023). "Here, we studied the role of the IL-25/ILC2 axis in lung cancer both in humans and in mice." (PMID 37781372, 2023). "The upregulation of MVP in lung cancer cells is related to interleukin 25 (IL-25) induction." (PMID 35681764, 2022). "Lung cancer is one of the cancers in which IL‐25 plays a supportive role in its development." (PMID 34128588, 2021). "Our data suggest that IL‐25 plays critical roles in promoting drug‐resistance of lung cancer cells." (PMID 31044552, 2019). "Resistance to chemotherapy in lung cancer patients might also be affected by IL-25." (PMID 37005677, 2023). "Overall, our results indicate that the IL-25/ILC2 axis promotes lung cancer potentially by recruiting immune-suppressive cells to the tumors both in humans and in mice, and that it may therefore represent a suitable novel target for NSCLC immunotherapeutic development." (PMID 37781372, 2023). "We analyzed the effect of adoptive transfer of IL-25-activated ILC2 cells on tumor growth, metastasis and survival in a heterotopic murine model of lung cancer." (PMID 37781372, 2023). "To further elucidate the relationship of IL‐25 and MVP in drug‐resistant lung cancer cells, we first explored the effect of IL‐25 on A549 and A549/CDDP cells responding to cisplatin treatment." (PMID 31044552, 2019). "In the present study, we occasionally found that IL‐25 and MVP expressions both increased in cisplatin‐resistant lung cancer cells (A549/CDDP)." (PMID 31044552, 2019). "We found that chitin exposure rapidly induced the expression of three key type 2-promoting cytokines, IL-25, IL-33 and TSLP, in BEAS-2B transformed human bronchial epithelial cells and in A549 and H292 lung carcinoma cells." (PMID 27463381, 2016).
lung carcinoma (continued). "Similar effects of chitin and Car/Thy on IL-25, IL-33, and TSLP were seen with H292 human lung mucoepidermoid carcinoma cells and A549 human lung carcinoma cells." (PMID 27463381, 2016). "Overall, our results suggest that the IL25/ILC2 axis bears pro-tumoral functions in human and mouse lung cancer, and that targeting it might represent a novel immunotherapy for patients with NSCLC." (PMID 37781372, 2023). "Elevated IL-25 stimulates the expression of MVP and activates the several intracellular processes, including the NF-κB signaling pathway, contributing to chemotherapy resistances of lung cancer cells." (PMID 35681764, 2022). "In order to test our hypothesis that the IL25/ILC2 axis bears tumor-promoting properties, we decided to examine the effect of adoptive transfer of IL25-activated ILC2 cells in lung tumor-bearing mice using the well-established Lewis lung carcinoma (LLc1) heterotopic model of lung cancer." (PMID 37781372, 2023). "However, the relationship between IL‐25 and MVP in lung cancer cells has not been studied." (PMID 31044552, 2019).
nematode infection (7 papers, 2012 to 2025). "Mice with IL-25 deficiency (IL-25−/−) develop severe intestinal inflammation during nematode infection implicating a pivotal role of IL-25 in gut mucosal homeostasis." (PMID 25937893, 2014). "Following nematode infection, Tuft cells in the intestinal epithelium secrete IL-25; this activates ILC2 which secrete IL-4 and IL-13." (PMID 40565065, 2025). "The production of IL-4 and IL-13 during nematode infection in vivo is mainly initiated by the alarmins IL-25, IL-33 and TSLP released by epithelial and stromal cells." (PMID 38414039, 2024). "Among the identified downstream effector molecules of IL-25, IL-13 is critical for the promotion of type 2 immunity important for clearance of parasitic nematode infections and for the characteristic changes in gut function after nematode infection." (PMID 25937893, 2014). "While other members of the IL-17 family have biological activities similar to Th1 inflammatory cytokines, IL-25 is involved in the promotion of type 2 immunity including allergy, asthma, and host immunity against parasitic nematode infection." (PMID 25937893, 2014). "Both IL-25 and IL-33 are upregulated during nematode infection and play an important role in host protective immunity." (PMID 23536877, 2013). "Interleukin (IL)-25 (also named IL-17E) is a member of the IL-17 cytokine gene family, and has been shown to play a critical role in the promotion of type 2 immunity, which is important against parasitic nematode infections." (PMID 31296243, 2019). "Interestingly, the production of IL-25 following nematode infection is itself dependent on IL-4Rα, mediated by IL-13 activation of STAT6." (PMID 30238872, 2018). "It remains to be determined whether macrophages can produce type 2 cytokines during nematode infection or in response to IL-25/IL-33." (PMID 23536877, 2013).
autoimmune disorders (6 papers, 2013 to 2026). "The IL-17 family includes six members, IL-17A, IL-17B, IL-17C, IL-17D, IL-17E (also known as IL-25), and IL-17F, which play a crucial role in autoimmunity, cancer, and other inflammatory conditions." (PMID 33562334, 2021). "Treatment with OA also reduced the indices of inflammation and autoimmunity in colon tissues, (i.e., increased TNFα, IL-1β, IL-23, IL-17A, and KC; and reduced IL-13, IL-33, and IL-25)." (PMID 33246492, 2020).
experimental autoimmune encephalomyelitis (6 papers, 2016 to 2026). An autoimmune demyelinating disease of the central nervous system that is produced experimentally in animals by the injection of homogenized brain or spinal cord in Freund's adjuvant. "For example, IL-25 treatment suppresses Th17 responses and disease symptoms in experimental autoimmune encephalomyelitis (EAE) and is important in maintaining blood-brain barrier function." (PMID 27154002, 2016). "Additionally, IL-25 may suppress Th17 cell responses through downregulation of IL-23, IL-1β, and IL-6 expression in activated dendritic cells which may protect mice from severe experimental autoimmune encephalomyelitis." (PMID 34956328, 2021). "In experimental autoimmune encephalomyelitis (EAE), neutralization of IL-17, but not of IFN-γ, in IL-25−/− mice prevented EAE." (PMID 27812008, 2016).
idiopathic pulmonary fibrosis (6 papers, 2016 to 2025). Idiopathic pulmonary fibrosis (IPF) is a nonneoplastic pulmonary disease that is characterized by the formation of scar tissue within the lungs in the absence of any known cause. "For example, the cytokines IL-25 and IL-33 produced by epithelial cells induce Th2-type adaptive responses where increased expression of both cytokines has been found in patients with idiopathic pulmonary fibrosis (IPF), and IL-33 has an inhibitory effect on mast cell functions." (PMID 33562816, 2021).
liver fibrosis (6 papers, 2017 to 2024). "IL-25 is a Th2 cytokine, and according to the same study investigating rat airway inflammation, hepatic macrophages overexpress IL-25 and may contribute to liver fibrosis caused by C. sinensis." (PMID 28623940, 2017). "In previous reports, IL-25 was shown to perform a central task in the incidence of acute hepatitis (AH), liver fibrosis, and cirrhosis." (PMID 36119529, 2022). "Our previous work showed that IL-25 is significantly elevated in the serum of C. sinensis-infected mice, and this trend correlated with the degree of liver fibrosis during infection." (PMID 28623940, 2017). "In addition, IL-33 serum level was found to increase by liver fibrosis progression and viral load, in contrast to both IL-17 and IL-25." (PMID 35056005, 2022). "CsLysoPLA activates HSCs by upregulating IL-25 in macrophages through the PKA-dependent B-Raf/ERK1/2 pathway and potentially promotes hepatic fibrosis during C. sinensis infection." (PMID 28623940, 2017). "Contrarily to IL-33, current findings indicate that serum levels of IL-17 and IL-25 did not increase in HCV patients with higher viral loads or liver fibrosis." (PMID 35056005, 2022). "However, another study demonstrated an overlapping role of IL-33, IL-25, and TSLP in a schistosome-induced lung granuloma and liver fibrosis model." (PMID 32132991, 2020). "Hepatic fibrosis induced by S. mansoni is not affected by the lack of TSLP, IL-25, and IL-33 signaling individually, but disruption of signaling by all three mediators reduced hepatic fibrosis, eosinophils, and innate lymphoid cell (ILC)-2 in the liver of mice." (PMID 32922381, 2020).
breast tumor (5 papers, 2015 to 2022). "Nevertheless, our findings are consistent with the well-established role of IL-25 in boosting type 2 immune response and thereby enhancing tumor metastasis in breast tumor models." (PMID 27909985, 2017). "Inhibition of IL-25 resulted in decreased type 2 T cells and macrophages in the primary tumor microenvironments, both reported to enhance breast tumor invasion and subsequent metastasis to the lung." (PMID 27909985, 2017). "Here, we demonstrate that in MMTV-PyMT, a highly malignant spontaneous breast tumor model, IL-25 (also called IL-17E) was expressed by tumor-infiltrating CD4+ T cells and macrophages." (PMID 27909985, 2017). "In line with this evidence, treatment with anti-IL-25 blocking antibody significantly reduced IL-4-producing CD4+ Th2 cells in the MMTV-PyMT breast tumor model." (PMID 27909985, 2017). "Furthermore, IL-17E (IL-25) markedly reduces growth of MDA-MB468 breast tumor xenografts in vivo, while IL-17B increases it." (PMID 32373132, 2020). "For a further understanding of the clinical relevance of IL-25, we examined IL-25 expression in all the four major molecular subtypes of human breast tumors, including Luminal A, Luminal B, Triple negative/basal-like, and HER2-enriched types, by immunohistochemical analysis." (PMID 27909985, 2017). "IL-25 has been reported to express in breast tumor specimen." (PMID 27909985, 2017). "These contrasting data together highlights the complexity and heterogeneous nature of breast tumors, and thus IL-25 may play a distinct role in different tumor models." (PMID 27909985, 2017). "IL-25 was abundantly expressed in the primary sites of both human and mouse breast tumors, but not in the metastatic lung in the MMTV-PyMT tumor model." (PMID 27909985, 2017).
gastric cancer (5 papers, 2016 to 2023). A primary or metastatic malignant neoplasm involving the stomach. "Here the authors show that tuft cells and ILC2s are increased during gastric cancer development and that the pharmacologic inhibition of tuft cell derived IL25 or ILC2-produced IL13 reduces gastric tumor growth." (PMID 37898600, 2023). "In gastric cancer, Kaplan–Meier survival analysis demonstrated a positive correlation between the density of intra‐tumoral IL‐25+ macrophages and 5‐year or overall survival in patients." (PMID 34128588, 2021). "Taking together, these results showed that IL‐25+ macrophages, which inhibited the tumor progression, were a predictor biomarker of favorable survival in gastric cancer patients after resection." (PMID 34128588, 2021). "Tumor infiltrating macrophages could express interleukin 25, which was significantly related to the prognosis of gastric cancer after radical resection." (PMID 34025929, 2021). "In gastric cancer (GC) patients, it has been demonstrated that TGF‐β1 dose‐dependently induces tumor‐resident macrophages to produce IL‐25, which consequently promotes GC." (PMID 34128588, 2021). "The aim of this study was to investigate the cellular source and clinical significance of IL-25 in gastric cancer (GC) in situ." (PMID 26840565, 2016). "Therefore, it has been revealed that density of intra‐tumoral IL‐25+ macrophages, TNM stage, and tumor location were independent predictive biomarkers for overall survival in patients who have gastric cancer." (PMID 34128588, 2021). "Because the ligands of IL-17RB were IL-17B and IL-17E/IL-25, we quantitated the expressions of IL-17B and IL-17E mRNA in gastric cancer tissues and matched non-cancerous tissues by real-time quantitative PCR." (PMID 27146881, 2016).
Hepatic steatosis (5 papers, 2019 to 2025). Steatosis is a term used to denote lipid accumulation within hepatocytes. "Accordingly, another study demonstrated that exogenous IL-25 administration protects against hepatic steatosis through IL-13-induced activation of STAT6." (PMID 41409600, 2025). "The literatures have reported that IL-25 plays leading roles in fulminant hepatitis (FH), hepatic fibrosis and hepatic steatosis." (PMID 31296243, 2019). "Additionally, the administration of IL-25 reduced body weight, liver mass, and hepatic steatosis in HFD-induced NAFLD mice in the same study." (PMID 40794228, 2025). "IL-25 promotes hepatic macrophage differentiation towards the M2a phenotype, both in vivo and in vitro, via the IL-13/STAT6 pathway, alleviating HFD-induced hepatic steatosis." (PMID 41409600, 2025).
periodontitis (5 papers, 2018 to 2026). An acute or chronic inflammatory process that affects the tissues that surround and support the teeth. "In the paper that compared cytokine levels for 54 periodontitis patients and 40 healthy controls, cytokines IL‐1β, IL‐4, IL‐6, IL‐10, IL‐17A, IL‐17F, IL‐21, IL‐22, IL‐23, IL‐25, IL‐31, IL‐33, IFN‐γ, sCD40L and TNF‐α were measured in saliva and serum at baseline, 3, 6 and 12 months after treatment." (PMID 41580300, 2026). "High levels of IL-17A, IL-17F IL-22, IL-25, IL-33, IL-10 and INF-y were found in gingival biopsies compared with intestinal biopsies from patients with IBD and periodontitis." (PMID 34501547, 2021).
polyp (5 papers, 2016 to 2019). A usually exophytic mass attached to the underlying tissue by a broad base or a thin stalk. "We then examined the correlation between the IL-25 level and the activated NPDFs in the polyp tissues." (PMID 28771607, 2017). "Expressions of IFN-γ, IL-5, IL-17A, IL-25 and IL-10 were significantly higher in the 3 months and 6 months murine polyp model than in the control mice." (PMID 27584662, 2016). "TH2 cytokine expression was determined by means of flow cytometry in polyp explants cultured in the presence of recombinant human IL-25 or IL-33 to evaluate whether IL-17RB and ST2 expressed on polyp T cells were functional." (PMID 26684290, 2016).
amebic colitis (4 papers, 2017 to 2022). "In mouse model, we demonstrated that dysbiosis induced by antibiotic pre-treatment increased the severity of amebic colitis due to decreased neutrophil activity as well as decreased IL-25 associated mucosal defense in the gut." (PMID 28817707, 2017). "A type 2 cytokine, IL-25, mainly released from intestinal tuft cells, was shown to protect from amebic colitis and downregulated pro-inflammatory cytokines including TNFα, IL-17a, and IL-2312,13." (PMID 34400793, 2022). "IL-25 was suppressed in the colon of humans with amebic colitis and in the murine model, and repletion of IL-25 reduced E. histolytica infection and protected the gut epithelial barrier." (PMID 28246365, 2017). "The most important finding of our study is that the intestinal epithelial cytokine IL-25 protects against amebic colitis." (PMID 28246365, 2017). "Here, we demonstrate that the anti-inflammatory cytokine IL-25 is suppressed during E. histolytica infection in humans and in a mouse model of amebic colitis." (PMID 28246365, 2017). "We utilized the mouse model of amebic colitis to test the importance of IL-25 in defense against E. histolytica invasion." (PMID 28246365, 2017). "IL-25 provided protection from amebic colitis in an eosinophil-dependent process, as demonstrated by abrogation of protection by depletion of eosinophils with anti-Siglec-F." (PMID 28246365, 2017). "Human colon biopsy samples from controls (from the University of Virginia) and amebic colitis patients were stained for IL-25 by immunohistochemistry." (PMID 28246365, 2017). "Gut IL-25 and mucus protein Muc2, both shown to provide innate immunity in the mouse model of amebic colitis, were lower in antibiotic pre-treated mice." (PMID 28817707, 2017). "We tested the role of IL-25 by administering recombinant IL-25 (rIL-25) to mice during amebic colitis and discovered that IL-25 protected against amebic colitis and that this protection was eosinophil dependent and acted in part by suppressing TNF-α." (PMID 28246365, 2017). "In conclusion, we have found that IL-25 is suppressed during amebic colitis and that administration of IL-25 in a mouse model reduced E. histolytica trophozoite number, antigen load, and epithelial disruption in the cecum." (PMID 28246365, 2017). "IL-25 expression was decreased in humans and in the mouse model of amebic colitis." (PMID 28246365, 2017). "Increased gut eosinophil peroxidase (Epx) mRNA with IL-25 suggested that eosinophils could be important for protection against amebic colitis." (PMID 28246365, 2017). "We discovered that the intestinal epithelial cytokine IL-25 was suppressed during amebic colitis in humans and that protection could be restored in the mouse model by IL-25 administration." (PMID 28246365, 2017). "We hypothesized that an IL-25-induced influx of eosinophils would ultimately function to suppress gut inflammation to provide protection against amebic colitis." (PMID 28246365, 2017). "In addition to systemic and local induction of IL-13 and IL-5, a possible role of IL-25 can be hypothesized, as it has recently been shown in protection from amoebic colitis, acting via eosinophils and suppression of TNF-α through a new pathway of innate mucosal immune response." (PMID 31212833, 2019). "However, the role of IL-25 in amebic colitis remains unknown." (PMID 28246365, 2017). "For C. difficile infection, IL-25 acted by reducing host inflammation but not pathogen burden, whereas for amebic colitis, both pathogen burden and inflammation were suppressed." (PMID 28246365, 2017). "Moreover, we demonstrated that eosinophils induced by IL-25 may protect by suppressing TNF-α, as IL-25 suppressed TNF-α levels and neutralization of TNF-α prevented amebic colitis." (PMID 28246365, 2017).